RNY4P14 (RNY4 pseudogene 14)
Gene: Miscellaneous RNA gene on chromosome 13 (39,785,415 to 39,785,510, reverse strand). Ensembl gene ENSG00000200526.
Homologues: Orthologues: chimpanzee Y_RNA (100% identical), macaque Y_RNA (97% identical), guinea pig Y_RNA (91% identical). Paralogues in human: Y_RNA (92% identical), RNY4 (91% identical), RNY4P24 (91% identical), RNY4P7 (91% identical), RNY4P10 (90% identical), RNY4P3 (89% identical), RNY4P6 (89% identical), Y_RNA (89% identical), Y_RNA (88% identical), RNY4P17 (86% identical), RNY4P19 (86% identical), RNY4P13 (85% identical), and 92 more.